PTH (parathyroid hormone)
Diseases named in the same sentence as PTH in open-access papers (continued):
Sharing a sentence is not in itself a finding about the gene and the disease.
vitamin D deficiency (continued). "Vitamin D insufficiency is associated with increased PTH levels, accelerated cortical bone loss and an increased risk of fractures, and concluded the relationship between PTH and 25OHD decreases smoothly." (PMID 29190676, 2017). "In cases of prolonged vitamin D deficiency the parathyroid glands increase the PTH production in order to increase calcium levels by “stealing” it from the bones." (PMID 26942211, 2016). "Plasma parathyroid hormone levels decreased after vitamin D therapy, the expected biological response to correcting vitamin D deficiency." (PMID 27716304, 2016). "It is evident that vitamin D deficiency results in PTH elevation, and treatment is associated with normalization of PTH and lower Ca2+ levels." (PMID 27087013, 2016). "PTH levels were normal in all patients except 5 which present mild secondary hyperparathyroidism due to Vitamin D deficiency." (PMID 27906970, 2016). "The intact parathyroid hormone level was normal (66 ng/l) with severe vitamin D deficiency (25-hydroxy vitamin D: undetectable levels)." (PMID 26800885, 2016). "We don’t have data on parathyroid hormone (PTH), but we would expect to see increased PTH in approximately on third of the subjects with vitamin D deficiency." (PMID 27170258, 2016). "Vitamin D deficiency in PHPT patients is related to higher PTH levels, larger adenomas, and severe clinical evolution, including fibrous cystic osteitis and hungry bone syndrome in postsurgery." (PMID 27525132, 2016). "This signifies that, since circulating PTH increases in response to vitamin D deficiency or insufficiency, sufficient vitamin D levels appear to be necessary to maintain PTH at a physiologically stable state." (PMID 26478225, 2016). "Elevated levels of PTH as a consequence of chronic vitamin D deficiency have been linked to bone loss." (PMID 27699068, 2016). "In line with experimental data, vitamin D deficiency has been associated with a poor prognosis in adult patients with heart failure, and circulating PTH levels are related with an increased risk of cardiovascular events and mortality." (PMID 26955207, 2016). "In patients who present with normal levels of serum calcium, high PTH concentrations, and vitamin D deficiency, treatment with vitamin D can lead to the common hypercalcemic form of PHPT3." (PMID 27508075, 2016). "It has been reported that vitamin D deficiency caused an increase in parathyroid hormone (PTH), which increased insulin resistance and was associated with diabetes, hypertension, inflammation, and increased cardiovascular risks." (PMID 26799569, 2016). "Lower serum phosphorus and higher serum parathyroid hormone were significantly associated with both vitamin D deficiency and insufficiency (p < 0.05)." (PMID 26942211, 2016). "On the other hand, vitamin D deficiency along with secondary hyperparathyroidism promote hypertrophy of cardiomyocytes and vascular remodeling; studies suggest that PTH has a inflammatory effect, since it stimulates the release of cytokines." (PMID 27893863, 2016). "Vitamin D deficiency is generally associated with an increase in PTH, as similarly found in our results." (PMID 26951992, 2016). "Another possible link between vitamin D status and depressive symptoms is an elevated parathyroid hormone (PTH) level that has been linked to depressive symptoms and insulin resistance and is increased in the state of vitamin D deficiency." (PMID 27803154, 2016). "Accordingly, the objectives of the present study were to assess vitamin D status on basis of serum 25(OH)D concentrations and its relation to PTH in a sample of Egyptian schoolchildren and to identify the predictors for vitamin D deficiency and insufficiency." (PMID 26942211, 2016). "The known association of vitamin D insufficiency and increased risk of falls and fractures in the elderly was thought to depend on bone remodeling via the rise of PTH." (PMID 26000306, 2015).
vitamin D deficiency (continued). "It is noteworthy that most of the studies evaluating the association of vitamin D deficiency with renal anemia emphasize the role of inflammation and of PTH as the main mediators of these changes." (PMID 25781618, 2015). "VDR is observed in human adipocytes, and vitamin D deficiency is capable of up-regulating parathyroid hormone, thereby increasing free intracellular calcium in adipocytes, which blunts the lipolytic response to catecholamines and enhances lipogenesis." (PMID 26177638, 2015). "In this study, we show that vitamin D deficiency can be safely and inexpensively induced in rats within three weeks with negligible effects on PTH, Ca, and P levels." (PMID 25815325, 2015). "Both vitamin D deficiency and hypercalciuria are associated with increased parathyroid hormone, which leads to bone loss by bone resorption to maintain the blood calcium level." (PMID 26426028, 2015). "To overcome these shortcomings, we report the successful induction of vitamin D deficiency within three weeks, with stable serum PTH and minerals levels, in Wistar rats." (PMID 25815325, 2015). "Similar to the general population, vitamin D deficiency in these patients is associated with elevated concentrations of parathyroid hormone and bone turnover markers as well as low bone mineral density." (PMID 25883412, 2015). "Vitamin D deficiency has been reported to be associated with an increase in parathyroid hormone, which in turn is associated with decreased insulin sensitivity." (PMID 26488726, 2015). "The hallmark of vitamin D deficiency is elevated PTH levels; a hormone stimulated as a result of low serum calcium levels." (PMID 26435569, 2015). "The goal of this study was to determine the prevalence of vitamin D deficiency (hypovitaminosis D) and its association with serum calcium, phosphorus, and parathyroid hormone (PTH) concentrations, disease severity, and mortality in hospitalized newborn foals." (PMID 26046642, 2015). "The epidemiological association between vitamin D deficiency and high mortality rates extends beyond the abnormal mineral homeostasis that impairs bone mineralization due to high serum levels of PTH." (PMID 25815325, 2015). "Whenever a longer exposure to vitamin D deficiency is necessary, it is mandatory to control for the maintenance of normal calcium, phosphate, or PTH levels, to avoid compromising result interpretation." (PMID 25815325, 2015). "High PTH was seen in severe deficiency, deficiency and vitamin D insufficiency with rates ranging from 51.5% to 37%, but also in the sufficiency group in 33.2% of assessments." (PMID 26024516, 2015). "Several studies in critically ill patients report associations between vitamin D deficiency, a disturbed parathyroid hormone (PTH)-vitamin D axis and increased mortality." (PMID 25475621, 2014). "In vitamin D deficiency, there is a decrease in circulating levels of calcium and increased PTH levels." (PMID 24747593, 2014). "The clinical manifestations of CKD-MBD include imbalances in blood calcium (Ca) and phosphorus (Pi), vitamin D deficiency, increased levels of parathyroid hormone (PTH) and serum fibroblast growth factor-23 (FGF-23)." (PMID 24669256, 2014). "In our patient, the constellation of a low-normal serum calcium, low serum phosphorus, elevated alkaline phosphatase, increased parathyroid hormone and low 25-(OH)D3 are all typical of severe vitamin D deficiency." (PMID 26425621, 2014). "Vitamin D deficiency contributed to the elevation of plasma PTH and decrease of plasma FGF-23 levels as well as for important chronic tubulointerstitial changes." (PMID 25222475, 2014). "The very high PTH level observed in our first case (617 pg/mL) proved to be associated with severe vitamin D deficiency [25(OH)D 6.1ng/mL] and showed a rapid decrease after vitamin D stoss therapy." (PMID 24932605, 2014).
vitamin D deficiency (continued). "Analysis of PTH levels revealed secondary hyperparathyroidism (PTH ≥65 pg/ml) in 50.8% of obese patients as a whole, and 54.7% of those with vitamin D deficiency/insufficiency." (PMID 24618074, 2014). "The inverse association between magnesium intake and risk of vitamin D deficiency only appeared significant among those older than 50 years or with serum PTH level being in the highest or lowest tertile category." (PMID 23981518, 2013). "In this context, it should be noted that high parathyroid hormone (PTH) levels are a hallmark of vitamin D deficiency and are known to be associated with myocardial hypertrophy and higher blood pressure levels." (PMID 23912328, 2013). "MBDs can be characterized by fibrous osteodystrophy (classic MBD), osteopenia, or rickets, and are caused by high bone turnover secondary to calcium-phosphorus imbalance, malabsorption, vitamin D deficiency, and/or excess parathyroid hormone (PTH)." (PMID 24324827, 2013). "The included studies used different definitions of vitamin D deficiency, based either on levels of vitamin D or of parathyroid hormone (PTH), also using somewhat cutoff levels." (PMID 24106456, 2013). "Vitamin D deficiency leads to secondary hyperparathyroidism with PTH-enhanced 1,25(OH)2D production and is often associated with normal to high 1,25(OH)2D levels." (PMID 23306192, 2013). "Biochemical evaluation revealed low serum calcium (7.8 mg/dL), low phosphorus (1.4 mg/dL), vitamin-D deficiency [25-hydroxy-vitamin-D (25(OH)D): 8.7 ng/mL], and elevated intact parathyroid hormone (PTH, 811 pg/mL)." (PMID 24379038, 2013). "Significant predictors of vitamin D deficiency in the univariate analysis included BMI, African American race, and PTH." (PMID 23724340, 2013). "The present study sought to determine the prevalence of vitamin D deficiency among critically ill adults, characterise changes in the calcium-PTH-vitamin D axis and assess the effects of these changes on disease severity and prognosis." (PMID 24073266, 2013). "In the current study, we found magnesium intake was associated with a reduced risk of vitamin D insufficiency or deficiency only among those in the highest or the lowest tertile of PTH." (PMID 23981518, 2013). "Vitamin D deficiency and hypophosphatemic rickets can share similar biochemical findings of low phosphorus, elevated alkaline phosphatase, and PTH levels." (PMID 24386581, 2013). "Secondary hyperparathyroidism was also used as a definition of severe vitamin D deficiency in many studies, mostly based upon blood levels of PTH, with PTH values >7.6 pmol/L or >5.5 pmol/L as most commonly used, with PTH >6.9 pmol/L in one study." (PMID 24106456, 2013). "In animal models, vitamin D deficiency and high parathyroid hormone (PTH) levels have been linked with higher muscleprotein breakdown." (PMID 24128975, 2013). "Vitamin D deficiency is associated with lower levels of serum-ionized calcium, a stimulus leading to increased PTH levels." (PMID 23306192, 2013). "By contrast with the results from other study in HIV-infected patients, in our study, ionized calcium in the serum stayed within the normal range despite the vitamin D deficiency, suggesting an adaptive response to parathyroid hormone." (PMID 23295013, 2013). "Critically ill patients often show significant dysregulation of the calcium-PTH-vitamin D axis, and vitamin D deficiency is an independent risk factor for prognosis in serious illness." (PMID 24073266, 2013). "Vitamin D deficiency is an independent risk factor for 90-day mortality, and hypovitaminosis D in PTH-responders is associated with higher mortality than is the same condition in non-responders." (PMID 24073266, 2013). "Parathyroid hormone and 25(OH)D are inversely related; an increased concentration of PTH is a functional indicator of vitamin D deficiency and insufficiency." (PMID 22606373, 2012).
vitamin D deficiency (continued). "The normal physiological response to vitamin D deficiency is an increase in PTH stimulation and a subsequent reduction in renal phosphate reabsorption." (PMID 22984574, 2012). "In our results, vitamin D was negatively correlated to PTH levels (r = −0.176) and the PTH levels were significantly higher in the vitamin D deficiency group when compared with the sufficiency group." (PMID 22457762, 2012). "Our results confirm the results of other studies that show that obese individuals with higher BMI have a higher risk of vitamin D deficiency and elevated PTH serum concentrations." (PMID 23228198, 2012). "Primary hyperparathyroidism (pHPT) in postmenopausal women is frequently associated with vitamin D deficiency, which in turn is an additional stimulus for further increases in circulating parathyroid hormone (PTH) levels." (PMID 23781299, 2012). "Vitamin D deficiency (25(OH)D < 50 nmol/L was found in 84.6% of females and 67.5% of males (P < 0.008) and secondary hyperparathyroidism (PTH > 6.8 pmol/L) in 39.4% and 25.3%, respectively (P = 0.028)." (PMID 22518129, 2012). "In conclusion, long-term replacement of vitamin D deficiency with vitamin D in various commonly prescribed preparations effectively reduced circulating PTH levels." (PMID 23781299, 2012). "Secondary hyperparathyroidism is a classic sign of vitamin D deficiency, where low ionized calcium concentrations trigger a sensor in the parathyroid glands to increase PTH secretion." (PMID 22413062, 2012). "Cross-sectional data have linked tenofovir with higher parathyroid hormone (PTH) concentration in patients with vitamin D deficiency." (PMID 24052874, 2012). "In this study, we explored the effects of prolonged treatment with vitamin D on changes in circulating PTH and adjCa levels in postmenopausal women with pHPT and coexistent vitamin D deficiency." (PMID 23781299, 2012). "Conflicting reports support or refute an association between vitamin D deficiency with high levels of parathyroid hormone (PTH) and raised blood pressure or hypertension." (PMID 22937036, 2012). "Apart from the elevated markers of increased bone turnover, patients with coexisting pHPT and vitamin D deficiency are more likely to have a larger parathyroid adenoma and higher PTH levels." (PMID 23781299, 2012). "Vitamin D deficiency further increases circulating parathyroid hormone (PTH) levels in patients with primary hyperparathyroidism (pHPT), with potential detrimental effects on bone mass." (PMID 23781299, 2012). "The clinical relevance of our PTH findings are underlined by the fact that rising PTH levels are a hallmark of vitamin D deficiency and have been associated with adverse outcomes including mortality and cardiovascular events." (PMID 22518130, 2012). "Vitamin D levels should be obtained in all patients with increased PTH levels and normal blood calcium levels since vitamin D deficiency can result in calcium levels which are lower than expected in patients with primary hyperparathyroidism." (PMID 21747852, 2011). "After accounting for the effect of gestational age through multivariable regression, 25(OH)D status retained a significant negative association with PTH, confirming that even during pregnancy, PTH is a predictor of vitamin D deficiency." (PMID 21197089, 2010). "Some authors have considered the cut-off value for the definition of Vitamin D insufficiency as being 50.0 nmol/L because at values lower than this, there is a bone resorption associated with a PTH increase." (PMID 20546572, 2010). "Vitamin D deficiency results in elevated parathyroid hormone (PTH), which in turn is known to elevate intracellular calcium." (PMID 20011094, 2010). "Using both circulating 25(OH)D and PTH as markers of vitamin D deficiency, these findings underscore recent reports of widespread vitamin D deficiency among pregnant women, even in areas of the world with ample sunlight." (PMID 21197089, 2010).
vitamin D deficiency (continued). "These levels are often normal or elevated in the setting of vitamin D deficiency due to increased activity of renal 1-hydroxylase under the influence of elevated PTH." (PMID 20148079, 2010). "It was also shown that the regulation and action of PTH were disturbed in vitamin D deficiency, and restored after vitamin D treatment." (PMID 21274319, 2010). "Studies have shown that long-term vitamin D deficiency can result in increased PTH concentrations and decreased serum 1,25(OH)2D concentrations, which leads to osteomalacia." (PMID 17295904, 2007). "Low calcium intake can raise PTH levels, potentially leading to vitamin D deficiency." (PMID 41149617, 2025). "Likewise, the values obtained were correlated to the findings of the periodontal study of the patients, where the cause of the decrease in bone density was seen to be 25OH vitamin D deficiency and an increase in PTH levels." (PMID 39582410, 2025). "Serum parathormone (PTH) proved to be inversely correlated with 25-OH-D, whereas serum ionized calcium was significantly higher in SFs with 25-OH-D ≥ 30 ng/mL than in SF with a vitamin D deficiency (<20 ng/mL)." (PMID 39940323, 2025). "PTH-unrelated causes include renal insufficiency, vitamin D deficiency, and massive cellular lysis." (PMID 41181744, 2025). "Serum intact PTH level may also be elevated due to vitamin D deficiency, possibly secondary to hyperparathyroidism." (PMID 38525667, 2025). "Although low 25(OH)D is known to increase PTH secretion through physiological mechanisms, it is also possible that both vitamin D deficiency and elevated PTH levels are downstream effects of reduced sunlight exposure—a potential unmeasured confounder or mediator." (PMID 40431396, 2025). "Vitamin D deficiency reduces Ca absorption, increasing PTH secretion." (PMID 40292520, 2025). "Sixty percent had vitamin D deficiency, and 24·2% patients had elevated parathyroid hormone levels." (PMID 40697385, 2025). "However, further research demonstrated that aminoaciduria in vitamin D deficiency occurs independently of PTH levels." (PMID 41142409, 2025). "The authors hypothesized that PTH being elevated and negatively correlated with vitamin D levels was highly suggestive of secondary hyperparathyroidism associated with subclinical vitamin D deficiency." (PMID 39860501, 2025). "Of the 186 patients with mild hyperparathyroidism (45 ≤ PTH < 65 pg/mL), a total of 71.4% had abnormal concentrations of vitamin 25(OH)D < 30 ng/mL: 45/186 (24.1%) had vitamin D deficiency and 88/186 (47.3%) insufficiency, while the remaining 53/186 (29.5%) had vitamin D sufficiency." (PMID 40709988, 2025). "Misclassification is possible, as elevated PTH with normal calcium may reflect secondary causes such as vitamin D deficiency." (PMID 41323977, 2025). "Chronic elevations in PTH due to vitamin D deficiency may contribute to bone loss through pro-inflammatory pathways involving Th17 cells, TNF-α, and IL-17." (PMID 41301518, 2025). "Importantly, an increase in parathyroid hormone (PTH) due to vitamin D deficiency has been identified as a primary causal mechanism." (PMID 40521355, 2025). "While our current study focused on establishing a link between Aβ signaling and PHPT in the context of vitamin D deficiency, a fundamental role of Aβ in mediating PTH hypersecretion may extend to other forms of hyperparathyroidism." (PMID 40492090, 2025). "In a public health context, consistency across these inflection points would support the use of the 25(OH)D and PTH concentrations at their respective inflection points as thresholds to define vitamin D deficiency or elevated PTH, respectively, based on greater risks of inadequate bone mass accrual." (PMID 40139482, 2025). "The high PTH level found in the PMNE group may be a biochemical reflection of vitamin D deficiency in these children." (PMID 40506917, 2025).